ENSG00000251537 (novel tripartite motif-containing 16 (TRIM16) and CMT1A duplicated region transcript 1 (CDRT1) protein)
Gene: Protein-coding gene on chromosome 17 (15,571,491 to 15,651,653, reverse strand). Ensembl gene ENSG00000251537.
Genetic constraint (gnomAD): Loss-of-function variants: 57 observed, 91.56 expected, observed/expected ratio (o/e) 0.62, 90% interval 0.5 to 0.78. The synonymous counts are far from expectation, so gnomAD's model fits this gene poorly and the ratio says little. Missense variants: 742 observed, 1,033.1 expected, observed/expected ratio (o/e) 0.72, 90% interval 0.68 to 0.76. Synonymous variants: 289 observed, 389.73 expected, observed/expected ratio (o/e) 0.74, 90% interval 0.67 to 0.82.